CTLA4 (cytotoxic T-lymphocyte associated protein 4)
Diseases named in the same sentence as CTLA4 in open-access papers (continued):
Sharing a sentence is not in itself a finding about the gene and the disease.
Lewis lung carcinoma (8 papers, 2021 to 2024). "For instance, experimental induction of TLS with LIGHT-VTP therapy renders PNET and Lewis lung carcinoma (LLC) sensitive to ICB targeting cytotoxic T-lymphocyte-associated protein 4 (CTLA-4) and PD-1." (PMID 34122434, 2021). "In this preclinical study, we utilize a spontaneously metastasizing, immunologically “cold” Lewis lung carcinoma model (LLC) to test the capacity of anti-CTLA-4 and BEMPEG to prevent distant metastases after primary treatment with hypofractionated RT or surgical resection." (PMID 33937052, 2021). "We assessed the therapeutic effect of 7HP349 using a Lewis lung carcinoma (LLC1) model, another syngeneic non–T cell–inflamed tumor in the context of dual blockade of CTLA-4 and anti–PD-1." (PMID 35552271, 2022). "Similar results were obtained for 68Ga-grazytracer PET in mice bearing Lewis lung carcinoma (LLC) treated with anti–PD-1 and anti–CTLA-4 antibodies." (PMID 35788116, 2022). "Mice bearing Lewis Lung Carcinoma (LLC) tumors were treated with combinations of BEMPEG, anti-CTLA-4, and primary tumor treatment (surgical resection or RT)." (PMID 33937052, 2021). "In an LLC-OVA (Lewis lung carcinoma) tumor model, although tumors were unresponsive to anti-PD-L1 treatment in either wild-type or PI3KδD910A mice, tumors were reduced by anti-CTLA-4 treatment in wild-type but not PI3KδD910A mice." (PMID 38115208, 2023).
meningioma (8 papers, 2019 to 2024). A generally slow growing tumor attached to the dura mater. "It was found that the expression of CTLA-4 in meningioma tumor cells was consistently elevated in those harboring a mutation that disrupts the PI3K–AKT–mTOR pathway, and anti-CTLA-4 treatment inhibited autophagosome formation." (PMID 39104530, 2024). "PD-L2 and B7-H3 were found to be expressed on the surface of tumor cells at significantly higher levels than PD-L1 and CTLA-4 in Grade I and II meningiomas." (PMID 32982948, 2020). "Other checkpoint proteins expressed include PD-L2 and B7-H3 in meningiomas with alterations in the PI3K/AKT/mTOR pathway genes, CTLA-4 in CD3+ T cells in atypical meningiomas with PIK3CA or smoothened, frizzled class receptor (SMO) mutations, and the cancer/testis antigen NY-ESO-1." (PMID 37366884, 2023). "TRAF-7 mutated meningiomas demonstrated elevated levels of programmed death ligand-1 (PD-L1), the major ligand for the programmed death checkpoint pathway, while PD-L2 is highly expressed in PI3K/AKT/mTOR pathway mutations and CTLA-4 was frequently expressed in PIK3CA and SMO mutated tumors." (PMID 36033542, 2022). "Specifically, studies of the immune microenvironment in meningiomas have revealed that checkpoint molecules like NY-ESO-1, PD-L1, PD-L2, B7-H3, and CTLA-4 are expressed in meningiomas and may be at least partly responsible for the suppression of the anti-tumor immune response." (PMID 32982948, 2020). "Lesser-known immunomodulatory proteins, such as PD-L2, B7-H3, CTLA-4, and NY-ESO-1, were also identified as highly expressed molecules in meningiomas." (PMID 35892898, 2022). "Many studies reported that meningiomas often express PD-L1, which correlates with higher grade and worse prognosis, and other immune checkpoints, such as TIM-3, NY-ESO-1, PD-1, PD-L2, B7-H3, and CTLA-4." (PMID 38816839, 2024). "The use of ipilimumab (NCT03604976) targeting CTLA-4, and nivolumab (NCT03604978) targeting PD-1, as well as, both medications together (NCT02648997) in conjunction with stereotactic radiosurgery in recurrent atypical and anaplastic meningiomas is currently being investigated." (PMID 36033542, 2022).
Miscarriage (8 papers, 2015 to 2025). A pregnancy that ends at a stage in which the fetus is incapable of surviving on its own, defined as the spontaneous loss of a fetus before the 22th week of pregnancy. "Altered frequency and function of Tim-3+CTLA-4+dCD8+ T cells were associated with miscarriage." (PMID 31138782, 2019). "In summary, we concluded the higher co-expression of Tim-3 and CTLA-4 on dCD8+ T cells during normal pregnancy, and decreased Tim-3 and CTLA-4 on dCD8+ T cells might be associated with miscarriage." (PMID 31138782, 2019). "We also established an abortion-prone model by female CBA/J × male DBA/2 mice, and observed similar phenomenon that decreased number and disordered function of Tim-3+CTLA-4+dCD8+ T cells in miscarriage." (PMID 31138782, 2019). "Therefore, the ratios of CTLA-4+/CD28+ in miscarriage were significantly lower than in normal pregnancy, both in peripheral blood and the decidua." (PMID 39941063, 2025). "Previous studies of CTLA-4 expression have shown a statistically significant relationship with the incidence of spontaneous miscarriage; however, the data are conflicting, and little is known about CTLA-4 in the endometrium or the decidua of women with a history of RPL." (PMID 37685876, 2023). "As the frequency and function of Tim-3+CTLA-4+dCD8+ T cells were both altered in miscarriage, we further tested whether blocking the Tim-3 and CTLA-4 pathways could change the functionalities of dCD8+ T cells." (PMID 31138782, 2019). "Furthermore, the decreased number and altered function of Tim-3+CTLA-4+dCD8+ T cells correlated to miscarriage." (PMID 31138782, 2019). "In decidual tissues from human miscarriage, the mRNA expression of CD28 was increased, while the expression of CTLA-4 mRNA (the checkpoint marker) was decreased." (PMID 39941063, 2025). "In the present study, efficacy studies of anti-CTLA-4 and anti-Tim-3 were first done in mouse pregnancy models, and then the expression and function of CTLA-4/Tim-3 on CD4+T cells during normal pregnancy and miscarriage were explored." (PMID 30622243, 2019). "Furthermore, the expression of CTLA-4 on the surface of CD4+CD25high cells, a molecule responsible for inhibition of T cell proliferation and transmission of the inhibitory signals, was increased in normal early pregnancy, and reduced in miscarriage." (PMID 25945787, 2015).
periodontitis (8 papers, 2018 to 2025). An acute or chronic inflammatory process that affects the tissues that surround and support the teeth. "For instance, the inhibition of Tregs with anti-GITR in an A. actinomycetemcomitans-induced model of periodontitis showed increased alveolar bone loss associated with the reduction of IL-10, CTLA-4, and TGF-β levels." (PMID 29805313, 2018). "The current article elaborates on the immuno-inflammatory pathways, molecular links, and plausible mechanisms linking periodontitis-associated CTLA-4 elevation and CTLA-4-based molecular therapy, specifically focusing on cancer immunotherapy." (PMID 41395347, 2025). "Investigate the genetic variations of PTPN22, PADI4, and CTLA4 and their impacts on RA and periodontitis." (PMID 39811802, 2025). "In the current article, an extensive literature review is conducted to elicit the link between the elevation of CTLA-4 in periodontitis and its possible influence on systemic immune-inflammatory disorders and their related targeted immune therapies." (PMID 41395347, 2025). "CTLA-4, PD-1, and PD-L1 were proven to play crucial roles in the progression of periodontitis and cancer." (PMID 41395347, 2025). "Periodontitis influences the serum levels of CTLA-4, which in turn alters the T cell activation pathways, PD-1 pathways, and CD80 activation, which has a key role in antigen presentation and implicates the B cell-mediated antibody response in periodontitis." (PMID 41395347, 2025). "For instance, there is a higher frequency of CD4+ CD25+ CTLA-4+ Tregs in periodontitis biopsies than in gingivitis." (PMID 29805313, 2018). "We also found PDCD1 was highly upregulated in the CD4_CTLA4 cluster from periodontitis, which indicates that PD-1 pathway may contribute to the protective effect of Treg in disease stage." (PMID 34566966, 2021). "Furthermore, CTLA4 was supposed to be involved in suppression of osteoclast differentiation and activation an important advance in the etiology of periodontitis." (PMID 33059697, 2020). "Inflammation of the oral mucosa manifesting as nonspecific stomatitis, periodontitis, and lichenoid reaction is relatively common and, in fact, better documented under treatment with PD-1/PD-L1 inhibitors, as opposed to CTLA-4 inhibitors." (PMID 37370736, 2023). "Interestingly, maximal expression of Treg-related genes Foxp3, IL-2, IL-10, CTLA-4, CD25, and GITR was reached later than Th17-related genes, on day 15 post-periodontitis induction." (PMID 33149125, 2020).
soft tissue sarcoma (8 papers, 2017 to 2023). A malignant neoplasm arising from muscle tissue, adipose tissue, blood vessels, fibrous tissue, or other supportive tissues excluding the bones. "Currently, the activity of dasatinib in combination with the CTLA4 inhibitor ipilimumab is being assessed in a phase I trial in unresectable or advanced soft tissue sarcoma (NCT01643278)." (PMID 27732970, 2017). "A new phase II study (NCT02500797) for ipilimumab (anti-CTLA-4) with or without nivolumab (anti-PD1) is currently accruing patients with unresectable or metastatic bone or soft tissue sarcoma." (PMID 27732970, 2017).
Stroke (8 papers, 2010 to 2025). Sudden impairment of blood flow to a part of the brain due to occlusion or rupture of an artery to the brain. "Our in vitro data suggest that the catecholamine release following stroke is causally related with the inhibition of CTLA-4 induction in activated T cells." (PMID 20090932, 2010). "This activation persisted in the subacute post-stroke phase and declined at 3 months post stroke, being accompanied by upregulation of PD-L1 and CTLA-4." (PMID 41373643, 2025). "In stroke and other cerebrovascular conditions, impaired CTLA-4 expression can lead to excessive inflammation, while CTLA-4 activation via regulatory T cells supports neuroprotection and offers a promising target for immunomodulatory therapies." (PMID 40943153, 2025). "Extending observation to 3 months post stroke thus enabled assessment of the transition from persistent activation to re-emerging inhibitory signaling through CTLA-4 and PD-L1." (PMID 41373643, 2025). "This concept is supported by prior studies linking impaired CTLA-4 or PD-1/PD-L1 signaling to post-stroke immune dysregulation and poor neurological recovery." (PMID 41373643, 2025). "Collectively, these findings suggest that both CTLA-4 and PD-1/PD-L1 pathways play crucial roles in modulating post-stroke inflammation and recovery, offering potential targets for therapeutic intervention." (PMID 40943153, 2025). "While decreased checkpoint expression has been reported in ischemic conditions, the definitive mechanistic pathways through which stroke alters CTLA-4 and PD-L1 signaling remain insufficiently understood." (PMID 41373643, 2025). "CTLA-4 signaling has been identified as a dominant immune pathway activated within 24–48 h following ischemic stroke, indicating its role in post-stroke immune suppression." (PMID 40943153, 2025). "Compared to healthy controls, stroke patients demonstrated an enhanced surface expression of HLA-DR (p<0.0001) and CD25 (p = 0.02) on T cells, revealing that stroke leads to T cell activation, while CTLA-4 remained undetectable." (PMID 20090932, 2010). "The delayed normalization of CTLA-4 and PD-L1 expression may represent a potential therapeutic window within which to restore immune homeostasis after stroke." (PMID 41373643, 2025). "The amount of CTLA-4+ on CD4+ T cells tended (p = 0.26) to be highest in the “stroke t3” group." (PMID 41373643, 2025). "Inhibitory activation markers CTLA-4 and PD-L1 were upregulated only 3 months after stroke." (PMID 41373643, 2025). "Our data point towards two mechanisms which may mediate the activation of T cells in stroke patients: while increased HMGB1serum levels may activate surviving lymphocytes in stroke patients a downregulatory mechanism, the expression of CTLA-4 remains suppressed." (PMID 20090932, 2010). "Nevertheless, our knowledge of the course of T cell activation in patients post stroke is still very limited: Data are available mainly on CD4+ T cells, few activation markers (HLA-DR, CD25, CTLA-4), and for a limited time span of 14 days." (PMID 41373643, 2025). "In whole blood from stroke patients, the activation markers CD25, CTLA-4, and PD-L1 were quantified on CD4+ or CD8+ T cells at 3 days (t1), 1 month (t2), and 3 months (t3) post stroke and compared to old as well as young controls for age effects." (PMID 41373643, 2025). "T cell subpopulations (CD4+, CD8+, DNT) and their activation (CD25, CD57, CTLA-4 (CD152) and PD-L1 (CD274)) were analysed in peripheral blood from stroke patients and controls by flow cytometry." (PMID 41373643, 2025). "Taken together, these observations suggest that disrupted CTLA-4 and PD-L1 signaling and altered DNT–microglia crosstalk may contribute to persistent T cell activation after stroke." (PMID 41373643, 2025). "We hypothesized that stroke-induced catecholamines and steroids could account for the lack of CTLA-4 upregulation and examined the influence of these hormones on CTLA-4 expression in vitro." (PMID 20090932, 2010).
ulcerative colitis (8 papers, 2009 to 2024). An inflammatory bowel disease involving the mucosal surface of the large intestine and rectum. "Similarly, in an ulcerative colitis model, anti–CTLA-4 antibodies led to the loss of efficacy of adoptively transferred Tregs without affecting the function of Tconv cells." (PMID 38426492, 2024). "We, therefore, generated a dataset using colon biopsies from patients with active ulcerative colitis (UC) and healthy control subjects without intestinal inflammation to see if CTLA4 expression was upregulated under inflammatory conditions in the human colon." (PMID 39496592, 2024).
bone sarcoma (7 papers, 2017 to 2023). A sarcoma that arises from the bone. "Aggressive pediatric bone sarcomas exhibited an increased number of peripheral CD14+HLA-DRlow/neg immunosuppressive monocytes as well as an increase of cytotoxic T-Lymphocyte Associated protein 4 (CTLA4+) and CD14+ macrophage infiltrates." (PMID 37424864, 2023). "In a recently reported single-center phase 2 trial evaluating durvalumab, an anti-PD-L1 drug, and tremelimumab, an anti-CTLA-4 drug, in advanced or metastatic soft tissue and bone sarcomas, 20% (1/5) of patients with UPS showed an objective response." (PMID 36854710, 2023). "Herein, the recent advances of current immune checkpoint targets, such as anti-PD-1/PD-L1 and anti-CTLA-4 blockade, for the treatment of bone sarcoma have been reviewed." (PMID 35145371, 2022). "Combination of PD-1 and CTLA-4 blockade therapy in bone sarcoma have shown better response compared to single checkpoint inhibitor therapy." (PMID 33757216, 2021). "The combined treatment of PD-1 and CTLA-4 blockade therapy has shown even better responses compared with single checkpoint inhibitors in bone sarcoma." (PMID 34068946, 2021).
classical Hodgkin lymphoma (7 papers, 2017 to 2025). "However, PD-1 blockade has been associated with a lower incidence of severe IrAE in non-transplant settings compared to CTLA-4 blockade, and is clearly more effective across a number of malignancies, including classical Hodgkin lymphoma (cHL)." (PMID 28239465, 2017).
gastritis (7 papers, 2020 to 2025). Inflammation of the stomach. "Moreover, an increased severity is associated with anti-CTLA-4 therapy in addition to an increased incidence of all extraintestinal manifestations including mouth ulcers, anal fissures, and esophagitis/gastritis." (PMID 34660286, 2021). "The proportion of activated CD8+ TRM cells was low in health (<1%; Figure 2Div) and increased in anti–CTLA-4/PD-1 gastritis (30%–51%; Figure 2Div)." (PMID 34147519, 2021). "CD8+ TRM comprise the majority of T cells in the gastric mucosa in both health and anti–CTLA-4/PD-1 gastritis (Figure 2Dii–iii)." (PMID 34147519, 2021). "During H. pylori infection, CTLA-4 engagement would reduce immune response and promote the development of stomach inflammation." (PMID 32547867, 2020).
giant cell arteritis (7 papers, 2015 to 2025). "Here, the authors also showed via transcriptomic data that CTLA-4-related pathways are upregulated in the circulating CD4+ T-cell compartment of patients with giant cell arteritis, while in aortic samples, gene expression of CD4+ T cells was also altered." (PMID 39023770, 2025). "Similarly, in a pharmacovigilance study, CTLA-4, but not PD-1/PD-L1 inhibition, was associated with over-reporting of giant cell arteritis." (PMID 39023770, 2025). "In giant cell arteritis, the balance between co-stimulatory signals (such as CD28) and co-inhibitory (such as CTLA-4 and PD-1) determines the level of inflammatory activity within the blood vessel walls." (PMID 39023770, 2025). "A large retrospective pharmacovigilance study of the World Health Organization’s Global Database for Case Safety identified an increased incidence of giant cell arteritis following ICI therapy, especially after CTLA-4-targeted therapy." (PMID 39023770, 2025).
gynecological cancers (7 papers, 2020 to 2025). "In this review, we aimed to summarize the mechanisms of actions of various ICIs, namely PD-1 inhibitors, PD-L1 inhibitors, and anti-CTLA-4 antibodies; mechanisms that cause irAEs; cases of ICI use in gynecological cancer; and clinical symptoms and appropriate management of various irAEs." (PMID 36674491, 2023). "Therefore, immune checkpoint inhibitor (ICI) therapy products, including PD-1/PD-L1 inhibitors and CTLA-4 inhibitors, are in the spotlight as alternatives for the treatment of advanced gynecological cancers." (PMID 36674491, 2023). "However, anti-CTLA-4 therapy’s potential in gynecological cancers is underexplored, and its modest monotherapy efficacy suggests combination strategies may better overcome immunosuppressive barriers." (PMID 41029427, 2025). "However, we observed that the expression pattern of both genes was consistent in tumor tissues of gynecological cancers (i.e., Uterine Carcinosarcoma [UCS] and Uterine Corpus Endometrial Carcinoma [UCEC]) compared with tumor-adjacent controls, and this difference was more noticeable for CTLA4." (PMID 38201508, 2023).
hepatitis B (7 papers, 2009 to 2025). "In a study of HCC patients treated with tremelimumab (a CTLA-4 inhibitor) in combination with ablation, five patients with hepatitis B were enrolled." (PMID 31312140, 2019). "Furthermore, CTLA-4 levels were significantly higher in hepatitis B patients with genotypes GG and AG compared to others with AA (p<0.001)." (PMID 37767077, 2022). "CTLA-4 level can be influenced by the CTLA-4 gene polymorphism (Corvalan, Carrasco and Saavendra, 2012), but no study has explored its relationship with response to hepatitis B treatment." (PMID 37767077, 2022).
interstitial lung disease (7 papers, 2017 to 2024). A diverse group of lung diseases that affect the lung parenchyma. "For example, CTLA4-Ig was reported to have fewer adverse effects on interstitial lung diseases than other bDMARDs and thus is preferred in such types of D2T RA." (PMID 35232462, 2022). "A recent study shows that abatacept, a CTLA4 fusion protein, was safe and effective in the treatment of CVIDid with interstitial lung disease." (PMID 34247288, 2021). "Abatacept (CTLA4-Ig) is a fusion protein consisting of an IgG1 Fc domain fused to the CTLA-4 extracellular domain that has successfully been used to control autoimmune inflammation and interstitial lung disease in patients with CTLA-4 haploinsufficiency and LRBA deficiency." (PMID 33613511, 2020).